SRF (serum response factor)
Diseases named in the same sentence as SRF in open-access papers (continued):
Sharing a sentence is not in itself a finding about the gene and the disease.
colorectal cancer (6 papers, 2010 to 2023). A primary or metastatic malignant neoplasm that affects the colon or rectum. "Given that ELK/SRF promotes cell growth, we observed that NLK deficiency significantly inhibited cell cycle progression and cell growth in colorectal cancer." (PMID 35013153, 2022). "SRSF3 is co-expressed with SRF in colorectal cancer tissues, and required for SRF expression." (PMID 37416784, 2023). "Furthermore, overexpression of SRF in colorectal cancer has been reported to decrease E-cadherin expression and increase nuclear β-catenin expression." (PMID 23426188, 2013). "Knockdown of SRSF3 expression significantly inhibits VEGF (vascular endothelial growth factor) expression in colorectal cancer cells, cancer cell migration, and tube formation by human umbilical vein endothelial cells (HUVECs) in vitro via a proangiogenic SRF (serum response factor) gene." (PMID 37416784, 2023). "The cis-regulatory sequences of genes down-regulated on blocking the MEK/ERK pathway in colorectal cancer cells clearly differ from those of growth factor stimulated genes which for example harbor binding sites for the transcription factors ATF/CREB, NFκB and SRF." (PMID 21170361, 2010).
Hyperglycemia (6 papers, 2018 to 2025). An increased concentration of glucose in the blood. "The expression of miR-1 and SRF was increased during hyperglycemia, and after the knockdown of SRF, the transcription and expression of miR-1 were inhibited, suggesting that miR-1 was positively regulated by SRF." (PMID 34646152, 2021). "EGFR signalling and SRF activation are redox-sensitive offering an explanation for the potentiating effect of hyperglycaemia." (PMID 32548701, 2020). "The impact of hyperglycaemia on EGFR-induced signalling and SRF transcriptional activity and the underlying mechanisms were investigated at the cellular level." (PMID 32548701, 2020). "In this process, the level of miR-133 was also regulated by its upstream modulator SRF, which constituted a hyperglycaemia/SRF/miR-133/ERG/IKr axis to modulate the current in cardiomocytes." (PMID 30174600, 2018). "Our data are comparable to these previous observations; specifically, in the current work, SMC-specific OGT deletion reduced SRF expression concomitant to attenuated PCNA expression in the aortic vasculature of smOGTKOApoE-/- following Western diet-induced hyperglycemia." (PMID 37175604, 2023). "As such, we speculate that interaction of YY1- and SRF-dependent pathways drive OGT-mediated SMC transformation to a de-differentiated phenotype in response to hyperglycemia." (PMID 37175604, 2023). "Our current findings prompt us to speculate that YY1- and SRF-dependent pathways play a regulatory role in OGT-mediated SMC de-differentiation induced by hyperglycemia, promoting accelerated atherosclerotic lesion formation in diabetes." (PMID 37175604, 2023). "Future studies, currently underway, are warranted to decipher the molecular link between O-GlcNAcylation and YY1/SRF-dependent pathways and delineate its role in VSMC fate switch in response to hyperglycemia." (PMID 40940776, 2025).
leukemia (6 papers, 2017 to 2023). A malignant (clonal) hematologic disorder, involving hematopoietic stem cells and characterized by the presence of primitive or atypical myeloid or lymphoid cells in the bone marrow and the blood. "Using in vivo functional approaches combined with molecular mechanistic analysis, we identified a reciprocal regulatory loop between B cell lymphoma 6 (Bcl6) and the RhoA-regulated transcriptional complex megakaryoblastic leukemia/serum response factor (MKL/SRF)." (PMID 37967194, 2023). "Furthermore, we found that promyelocytic leukaemia bodies are important in CRAG-induced SRF activation." (PMID 31882856, 2019). "For example, GATA1 partners with HNF1 in hematopoietic progenitor cells; with PPARA:RXRA in leukemia; with SRF, CDX and FOXP3 in primary T-cells; with SRY, NKX2-1, FOXF1, OCT4 and ZBTB16 in differentiated ESCs and with TAL1:TCF3 motif co-occurring in various fibroblasts." (PMID 30142147, 2018). "Furthermore, CRAG and ELK1 interact with promyelocytic leukaemia bodies through SUMO-interacting motifs, which is required for SRF activation." (PMID 31882856, 2019).
lung fibrosis (6 papers, 2015 to 2025). "CTGF and SRF, two genes quite strongly associated with lung fibrosis in previous studies, were upregulated at the mRNA level in IPF fibroblasts in the present meta-analysis." (PMID 27983601, 2016). "SRF is essential for collagen-1 expression by lung fibroblasts in vitro, while inhibition of the SRF pathway by the small molecule CCG-203971 attenuates lung fibrogenesis in the bleomycin-induced lung fibrosis model in mice." (PMID 27983601, 2016). "Since MKL1/SRF are known mediators of myofibroblast differentiation, we hypothesized that loss of MKL1 would attenuate pulmonary fibrosis." (PMID 25885656, 2015). "In light of this, targeting MKL1/SRF may be a useful strategy for disrupting myofibroblast function during pulmonary fibrosis." (PMID 25885656, 2015). "In pulmonary fibrosis, MRTF-A interacts with the serum response factor (SRF) in the nuclear matrix and promotes transcription of COL1A2 and TGF-β1, which increases the stiffness of ECM." (PMID 35250619, 2022). "Genes such as SRF, a key MRTF co-factor that is requisite for the induction of pulmonary fibrosis in mouse models, displayed elevated levels of promoter accessibility in Thy-1KO fibroblasts on soft substrates relative to WT but failed to respond to increases in substrate stiffness." (PMID 41212903, 2025). "Furthermore, our group has observed that signaling via protein kinase A (PKA) can protect against bleomycin-induced pulmonary fibrosis in mice, and that this protective effect is likely via inhibition of MKL1/SRF in myofibroblasts." (PMID 25885656, 2015).
megakaryocytic acute leukaemia (6 papers, 2013 to 2025). "MRTFA is associated with acute megakaryocytic leukemia, acts as a coactivator of SRF, and inhibits activation of caspases, which suppresses apoptosis." (PMID 31548358, 2019). "In addition, WIP has been identified as an MKL (Megakaryocytic leukemia)-dependent serum response factor (SRF)-target gene." (PMID 35927758, 2022). "This process depends on the ratio of F- to G-actin and activation of serum response factor (SRF) and its co-factor megakaryocytic acute leukaemia (MAL)." (PMID 40726337, 2025). "JunB is a direct target of serum response factor (SRF), a ubiquitous transcription factor involved in smooth muscle proliferation, differentiation and contractility, along with megakaryocytic acute leukemia (MAL), an SRF coactivator." (PMID 23308222, 2013). "With LIM kinase upregulation, MAL (megakaryocytic acute leukemia) can no longer be sequestered by actin monomers and translocates to the nucleus, where it activates SRF (serum response factor), a factor that responds to morphological changes in the actin cytoskeleton." (PMID 36901722, 2023).
Alzheimer disease (5 papers, 2008 to 2025). A progressive, neurodegenerative disease characterized by loss of function and death of nerve cells in several areas of the brain leading to loss of cognitive function such as memory and language. "In humans, SNPs in CArG box (SRF transcription factor binding site), that disrupt SRF binding, were linked with neurological disorders, such as bipolar disorder, amyotrophic lateral sclerosis, and Alzheimer’s disease." (PMID 31375980, 2019). "An increased expression of SRF and cognate target genes in vascular smooth muscle cells seems to account for the arterial hypercontratility observed in Alzheimer disease." (PMID 19079548, 2008). "In Alzheimer's disease, overexpression of SRF and myocardin in small cerebral arteries was shown to contribute to the pathogenesis of the condition as they increase arterial contractility and reduced blood flow due to the activation of SRF‐dependent SM contractile genes." (PMID 32885587, 2021). "For instance, transcription factors such as SRF and MYOCD are highly expressed in Alzheimer’s disease." (PMID 40166460, 2025).
glioma (5 papers, 2013 to 2025). A benign or malignant brain and spinal cord tumor that arises from glial cells (astrocytes, oligodendrocytes, ependymal cells). "RTVP-1 expression is induced in glioma cells by the protein kinase C (PKC) isoforms, PKCα and PKCε, via phosphorylation of the transcription factor serum response factor (SRF)." (PMID 26305187, 2015). "Regarding glioma, a substance isolated from the fruitbody of Trogia venenata (commonly known as little white mushroom) named Phragmunis A, was found to exhibit cytotoxicity on glioma cells via targeting of the ELK1/SRF complex." (PMID 40862737, 2025).
ischemic stroke (5 papers, 2014 to 2022). A stroke disorder caused by obstruction of blood flow to the brain, due to thrombotic (local blood clot formation) or embolic (due to a blood clot or other material traveling from another site) event. "In conclusion, our data delineate a previously unrecognised pro-survival pathway after ischaemic stroke: IRF4 initiates SRF transcription in neurons, which in turn promotes the expression of a myriad of SRF-dependent neuroprotective factors." (PMID 24510125, 2014). "The expression levels of SRF, ELK1, SREBP1, and NRF-2 have been shown to increase in ischemic stroke models." (PMID 29856744, 2018). "The interacting partners of HDAC4, MEF2, Runx2, SRF, HP1, ATF4, and NF-κB might also mediate its role in inhibiting neuronal death and promoting angiogenesis and neurogenesis in ischemic stroke." (PMID 30208931, 2018).
pancreatic cancer (5 papers, 2017 to 2023). "The ability of MICAL2 to regulate the SRF/MRTF-A target genes was also seen when we examined a pancreatic cancer gene expression analysis." (PMID 38137053, 2023). "Mechanistically, monensin suppresses numerous cancer-associated pathways, such as E2F/DP1, STAT1/2, NFkB, AP-1, Elk-1/SRF, and represses EGFR expression in pancreatic cancer lines." (PMID 30559409, 2018).
sarcopenia (5 papers, 2008 to 2024). Progressive decline in muscle mass due to aging which results in decreased functional capacity of muscles. "Moreover, the deletion of SRF in skeletal muscle caused a significant reduction in muscle mass, resulting in perinatal death, and conditional deletion of SRF in adult mice caused progressive muscle mass loss and sarcopenia." (PMID 38201213, 2023). "Several regulators (mammalian target of rapamycin, serum response factor, atrogin-1, myostatin, etc.)seem to modulate protein synthesis and degradation or transcription of muscle-specific genes during both sarcopenia and muscular dystrophy." (PMID 25221510, 2014). "Several positive and negative regulators (mTOR, SRF, atrogin-1, p62, and myostatin) have been proposed to enhance protein degradation or transcription of muscle-specific genes during both sarcopenia and muscular dystrophy." (PMID 25221510, 2014). "The aging process would alter this tissue-specific fine tuning of SRF expression and activity, leading in turn to the progressive development of further muscle alterations and sarcopenia in human skeletal muscles." (PMID 19079548, 2008). "The specific contribution of each of these factors is unknown, but there is emerging evidence using rodent muscle that the distribution of several positive regulators (Akt and SRF) of muscle hypertrophy with age is an important feature in the progression of sarcopenia." (PMID 25221510, 2014). "In fact, miR-28-5p targets two genes included in this pathway, namely Insulin-like growth factor-I (IGF-I) and serum response factor (SRF), both related to sarcopenia and that play a role as regulators of muscle atrophy." (PMID 39086897, 2024). "Most interestingly, we also observed decreased SRF levels in the skeletal muscle of aged mice and humans, suggesting that a naturally occurring decrease in SRF expression could contribute to the muscle phenotype observed during the aging process and in sarcopenia." (PMID 19079548, 2008).
schizophrenia (5 papers, 2018 to 2022). A major psychotic disorder characterized by abnormalities in the perception or expression of reality. "We have previously highlighted SRF as a protein in the proposed biological pathway for schizophrenia susceptibility based on its requirement for both novelty memory and LTD in mice, as well its regulatory interactions with other proteins in the pathway." (PMID 29520222, 2018). "Interestingly two NRG1 schizophrenia-associated SNPs from the original Icelandic haplotype occur in regions that show predicted binding sites for SRF that are abolished by presence of the SNPs." (PMID 29520222, 2018). "For instance, differential regulation of neuregulin 1 (NRG1) in schizophrenia is controlled by several 5′ SNPs that create/abolish binding sites for a string of transcription factors including SRF." (PMID 33520984, 2020). "Additionally, single nucleotide polymorphisms of SRF’s coactivators – MKL1 and MKL2 have been found in patients with schizophrenia and autism spectrum disorders." (PMID 35505150, 2022). "Dysbindin, a schizophrenia susceptibility marker and an essential constituent of BLOC-1 (biogenesis of lysosome-related organelles complex-1), has recently been associated with cardiomyocyte hypertrophy through the activation of Myozap-RhoA-mediated SRF signaling." (PMID 33142804, 2020). "Thus, SRF deletion in adult neurons recapitulates some aspects of morphological, electrophysiological, and behavioral changes that are observed in such psychiatric disorders as schizophrenia and autism spectrum disorders." (PMID 31375980, 2019).
Stroke (5 papers, 2013 to 2019). Sudden impairment of blood flow to a part of the brain due to occlusion or rupture of an artery to the brain. "For example, stroke-induced downregulation of miR-9 and miR-200b expression in the ischemic white matter region mediated serum response factor (SRF) induced differentiation of oligodendrocyte precursor cells (OPCs) into oligodendrocytes." (PMID 30984006, 2019). "For example, miR-9 and miR-200b are downregulated in ischemic white matter at two weeks after ischemic injury and regulate stroke-induced oligodendrogenesis by targeting the transcription factor serum response factor (SRF)." (PMID 28264471, 2017). "Using genetic manipulations, we further demonstrated that SRF is neuroprotective against stroke in vivo." (PMID 24510125, 2014). "Integrative transcriptional and cell survival analyses showed that IRF4 functions mechanistically as a transcription activator of serum response factor (SRF) crucial to salvage neurons during stroke." (PMID 24510125, 2014). "Mechanistically, we demonstrated that following stroke, IRF4 binds to the promoter region of SRF, thereby initiating SRF transcription." (PMID 24510125, 2014). "Thus, we speculated that in response to stroke, IRF4 upregulates SRF to counteract programmed neuronal death." (PMID 24510125, 2014).
Anxiety (4 papers, 2013 to 2023). Intense feelings of nervousness, tension, or panic often arise in response to interpersonal stresses. "A recent study identified SRF as a novel upstream mediator of FosB in nucleus accumbens after chronic social defeat stress, and implicated SRF in the development of depressive- and anxiety-like behaviors." (PMID 24124448, 2013). "Deletion of the SRF gene specifically in glutamatergic neurons has been reported to induce hyperactivity, decreased anxiety, and impair working memory." (PMID 36981011, 2023). "Furthermore, we found that both repressors inhibit a synthetic activity-dependent promoter with binding sites for CREB, MEF2, and SRF, and their simultaneous ablation in excitatory forebrain neurons leads to anxiety and deficits in memory that could not be detected in single KOs." (PMID 31375688, 2019).
epilepsy (4 papers, 2016 to 2022). A brain disorder characterized by episodes of abnormally increased neuronal discharge resulting in transient episodes of sensory or motor neurological dysfunction, or psychic dysfunction. "Employing adult SRF ablation in glutamatergic forebrain neurons (SrfCaMKCreERT2), we show here decreased epilepsy associated neurodegeneration, mossy fiber sprouting and inflammation." (PMID 28716058, 2017). "In summary, we show a role for SRF in epilepsy associated gene transcription, neurodegeneration, mossy fiber sprouting and inflammation." (PMID 28716058, 2017). "As expected, we found a large number of SRF-dependent genes associated with synaptic plasticity and epilepsy, the expression of which was decreased in SRF KO mice after seizures." (PMID 25636686, 2016). "Still, further studies are needed to determine which of the identified SRF target genes are actually involved in the development of epilepsy and what is the molecular mechanism underlying this process." (PMID 25636686, 2016). "We characterize the genetic program controlled by SRF in neurons and using functional annotation, we find that SRF target genes are associated with synaptic plasticity and epilepsy." (PMID 25636686, 2016). "SRF was required for epilepsy associated neurodegeneration, mossy fiber sprouting and inflammation." (PMID 28716058, 2017). "This suggests an SRF dependence on the epilepsy inducing agent and associated signaling pathways." (PMID 28716058, 2017). "We also identified 378 activity-dependent SRF target genes, among which we distinguished a group with functions associated with epilepsy and synaptic plasticity that may be responsible for the observed phenotype." (PMID 25636686, 2016). "In the present study, we show that the inducible and conditional deletion of SRF in the adult mouse hippocampus increases the epileptic phenotype in the kainic acid model of epilepsy, reflected by more severe and frequent seizures." (PMID 25636686, 2016). "We performed qPCR experiments and immunohistochemistry on tissue microarrays containing 286 GBMs to further explore the association of these candidate pathways and of markers of mesenchymal transformation (NF-κB, CEBP-β, STAT3, STAT5b, VEGFA, SRF) with epilepsy." (PMID 30621209, 2019). "Overall, we show first data on the role of SRF in MAP kinase signaling during epilepsy." (PMID 28716058, 2017). "Given this overlap between mouse models and TLE patients, SRF might be an important regulator and potential future therapeutic target in human epilepsy." (PMID 28716058, 2017). "We uncovered MAP kinase signaling as SRF target during epilepsy." (PMID 28716058, 2017). "In addition, SRF occupancy at IEG promoters and SRF phosphorylation, indicative of SRF activation, are enhanced in mouse epilepsy models." (PMID 28716058, 2017). "These proteins are induced by an increase in neuronal activity and appear to play a role as endogenous inhibitors of epilepsy; thus, impairment of their expression in SRF KO mice could enhance the epileptic phenotype, as demonstrated by the present results." (PMID 25636686, 2016). "Several SRF-controlled genes that were identified in the present study (e.g., Cyr61, Bdnf, Zfp36, Fos, JunB) are upregulated in the cortex in patients who suffer from epilepsy." (PMID 25636686, 2016). "Our data show that SRF is an important regulator of activity-induced gene expression in neurons and may be involved in the development of epilepsy." (PMID 25636686, 2016). "Altogether, we identified a group of novel SRF targets in neurons, which could explain the epilepsy-vulnerable phenotype observed in KO animals." (PMID 25636686, 2016). "What might be the role of these IEGs as SRF effector genes during epilepsy?" (PMID 28716058, 2017).